SPOP (speckle type BTB/POZ protein)
Description:
Component of a cullin-RING-based BCR (BTB-CUL3-RBX1) E3 ubiquitin-protein ligase complex that mediates the ubiquitination of target proteins, leading most often to their proteasomal degradation. In complex with CUL3, involved in ubiquitination and proteasomal degradation of BRMS1, DAXX, PDX1/IPF1, GLI2 and GLI3. In complex with CUL3, involved in ubiquitination of MACROH2A1 and BMI1; this does not lead to their proteasomal degradation. Inhibits transcriptional activation of PDX1/IPF1 targets, such as insulin, by promoting PDX1/IPF1 degradation. The cullin-RING-based BCR (BTB-CUL3-RBX1) E3 ubiquitin-protein ligase complex containing homodimeric SPOP has higher ubiquitin ligase activity than the complex that contains the heterodimer formed by SPOP and SPOPL. Involved in the regulation of bromodomain and extra-terminal motif (BET) proteins BRD2, BRD3, BRD4 stability. Plays an essential role for proper translation, but not for their degradation, of critical DNA replication licensing factors CDT1 and CDC6, thereby participating in DNA synthesis and cell proliferation. Regulates interferon regulatory factor 1/IRF1 proteasomal turnover by targeting S/T-rich degrons in IRF1. Facilitates the lysosome-dependent degradation of enterovirus EV71 protease 2A by inducing its 'Lys-48'-linked polyubiquitination, which ultimately restricts EV71 replication. Acts as an antiviral factor also against hepatitis B virus/HBV by promoting ubiquitination and subsequent degradation of HNF1A. In turn, inhibits HBV transcription and replication by preventing HNF1A stimulating activity of HBV preS1 promoter and enhancer II. Involved in ubiquitination of BRDT and promotes its degradation, thereby regulates histone removal in early condensing spermatids prior to histone-to-protamine exchange (By similarity).
Synonyms: TEF2; BTBD32; NEDMACE; NEDMIDF; NSDVS1; NSDVS2
Tractability: PROTAC: ubiquitination databases record sites on it.
Gene: Protein-coding gene on chromosome 17 (49,598,884 to 49,678,201, reverse strand). Ensembl gene ENSG00000121067.
Subcellular location: Nucleus; Nucleus speckle; Cytoplasm
Pathways (Reactome):
Immune System: SPOP-mediated proteasomal degradation of PD-L1(CD274)
Signal Transduction: Hedgehog 'on' state
Gene Ontology:
Molecular function: identical protein binding; molecular function inhibitor activity; protein binding; ubiquitin protein ligase binding
Biological process: proteasome-mediated ubiquitin-dependent protein catabolic process; protein polyubiquitination; regulation of proteolysis; protein ubiquitination
Cellular component: Cul3-RING ubiquitin ligase complex; cytoplasm; nuclear speck; nucleus; cytosol; nucleoplasm
Genetic constraint (gnomAD): Loss-of-function variants: 11 observed, 48.34 expected, observed/expected ratio (o/e) 0.23, 90% interval 0.14 to 0.38. The upper end of that interval is the gene's LOEUF score, 0.38, which puts it in group 1 of 6, group 1 being the genes least tolerant of losing a copy. Missense variants: 152 observed, 486.51 expected, observed/expected ratio (o/e) 0.31, 90% interval 0.27 to 0.36. Synonymous variants: 166 observed, 175.37 expected, observed/expected ratio (o/e) 0.95, 90% interval 0.83 to 1.08.
Gene-disease validity (ClinGen):
ClinGen rates the evidence that SPOP causes each of these diseases.
neurodevelopmental disorder with relative macrocephaly and with or without cardiac or endocrine anomalies (autosomal dominant): Definitive.
neurodevelopmental disorder with microcephaly and dysmorphic facies (autosomal dominant): Moderate.
Cancer hallmarks: genome instability and mutations (suppresses); escaping programmed cell death (suppresses); invasion and metastasis (promotes); suppression of growth (promotes); invasion and metastasis (suppresses)
Homologues: Orthologues: chimpanzee SPOP (100% identical), dog SPOP (100% identical), mouse Spop (100% identical), pig SPOP (100% identical), rabbit SPOP (100% identical), rat Spop (100% identical), guinea pig SPOP (99% identical), macaque SPOP (99% identical), tropical clawed frog spop (99% identical), zebrafish spop (97% identical), mouse Spopfm2 (58% identical), mouse Gm5773 (57% identical), and 15 more. Paralogues in human: SPOPL (84% identical), BTBD2 (20% identical), ABTB3 (20% identical), BTBD1 (20% identical), ABTB2 (18% identical), BTBD3 (18% identical), BTBD6 (16% identical), BTBD9 (15% identical), ABTB1 (11% identical), KBTBD4 (11% identical), KLHL11 (10% identical).
Diseases named in the same sentence as SPOP in open-access papers:
SPOP is named in the same sentence as 101 diseases in open-access papers, as found by Europe PMC text mining. Sharing a sentence is not in itself a finding about the gene and the disease. The quoted sentences say what the papers report.
prostate carcinoma (221 papers, 2013 to 2025). A carcinoma that arises from epithelial cells of the prostate gland. "The discovery of recurrent SPOP mutations in prostate cancer has sparked a transformative paradigm shift in our understanding of this disease." (PMID 40432836, 2025). "This review highlights the significance of SPOP mutations in prostate cancer, emphasizing their role in disrupting key cellular pathways and influencing clinical outcomes." (PMID 40432836, 2025). "Interaction with other genomic alterations: SPOP-mutated prostate cancers often exhibit distinct genomic alterations." (PMID 40432836, 2025). "Mutation frequency: SPOP mutations are frequent in prostate cancer, with prevalence ranging from 10% to 15% across different ethnic and demographic backgrounds." (PMID 40432836, 2025). "Other genes are involved in HR, such as speckle-type POZ protein (SPOP), a tumor suppression gene often mutated in prostate cancer, which is a E3 ubiquitin ligase adaptor protein." (PMID 40002869, 2025). "The identification of mutations in the BRAF and SPOP genes through genomic sequencing offers the potential for predicting the response to prostate cancer immunotherapy, assessing prognosis, and targeting therapy." (PMID 40492122, 2025). "Authors found that SPOP mutation in prostate cancer is associated with high level nanog expression and cell invasion." (PMID 41385185, 2025). "For instance, exon sequencing has revealed SPOP mutations in up to 13% of prostate cancers, where these mutations rank first among all altered genes and compromise substrate-binding capacity and oligomerization with SPOP." (PMID 40483310, 2025). "SPOP mutations are identified as early events in the development of a specific subtype of prostate cancer." (PMID 40432836, 2025). "SPOP mutations, which occur in approximately 10% of prostate cancers, seem to have an oncogenic role that is in part related to the impaired degradation of oncoproteins such as AR." (PMID 40075623, 2025). "These articles were chosen based on their direct relevance to SPOP mutations in prostate cancer, their contributions to disease characterization, and their insights into therapeutic implications related to the AR signaling pathway." (PMID 40432836, 2025). "This review aims to comprehensively summarize current knowledge on SPOP gene mutations in prostate cancer, emphasizing their importance in disease characterization and identification of therapeutic targets." (PMID 40432836, 2025). "The prevalence and functional consequences of SPOP mutations in prostate cancer are crucial for a comprehensive characterization of the disease." (PMID 40432836, 2025). "In this review, we explore the implications of SPOP mutations in prostate cancer, highlighting their significance for disease characterization and their potential as therapeutic targets." (PMID 40432836, 2025). "In prostate cancer, SPOP mutations disrupt the ubiquitination process, leading to aberrant stabilization and altered expression of epigenetic regulators, including BRD2." (PMID 40432836, 2025). "This highlights the potential for tailoring treatment strategies in prostate cancer based on SPOP mutation status." (PMID 40432836, 2025). "We further examined the effect of FTI treatment using lonafarnib in a clinically relevant setting with a patient-derived xenograft (PDX) model from a prostate cancer metastatic lesion harboring the SPOP F133L mutation and AR expression." (PMID 40662365, 2025). "The prognostic significance of SPOP mutations in prostate cancer remains an area of active research." (PMID 40432836, 2025). "In the context of prostate cancer, mutations within the substrate-binding cleft of the SPOP protein have been linked to aberrant protein interactions and degradation pathways, potentially contributing to cancer development." (PMID 40432836, 2025). "A systematic literature review was conducted to investigate the role of SPOP mutations in prostate cancer." (PMID 40432836, 2025).
prostate carcinoma (continued). "SPOP was the most highly mutated gene found in 13% of samples and follow-up work has now solidified SPOP loss-of-function mutations as robust drivers of prostate cancer." (PMID 40840524, 2025). "SPOP mutations are integral to the characterization of prostate cancer and the development of targeted interventions." (PMID 40432836, 2025). "The presence of SPOP mutations is linked to a notably high frequency of genomic rearrangements within prostate cancer cells." (PMID 40432836, 2025). "In this comprehensive review, we delve into the multifaceted role of SPOP mutations in prostate cancer, exploring their prevalence, functional consequences, clinical implications, and potential as therapeutic targets." (PMID 40432836, 2025). "These additional genomic alterations can contribute to the molecular and clinical heterogeneity of SPOP-mutated prostate cancer." (PMID 40432836, 2025). "SPOP mutations in prostate cancer predominantly occur within the MATH domain, which is essential for substrate binding." (PMID 40662365, 2025). "Mutations in the SPOP gene, which are frequently found in primary prostate cancer, stabilize GLI3, leading to its pathologic accumulation." (PMID 40432836, 2025). "The outcomes presented that the top 5 mutational frequency of SPOP mutation arise in endometrial cancer, breast carcinoma, embryonal cancer, pancreatic cancer, and prostate cancer." (PMID 39074086, 2024). "Systematic sequencing studies have demonstrated that SPOP presents high-frequency mutations in human cancer samples, especially in prostate cancer and endometrial cancer." (PMID 38409107, 2024). "Exon sequencing identifies SPOP mutations in up to 13% of prostate cancer (PC) samples, ranking first among all mutated genes." (PMID 38409107, 2024). "NEO2734 efficiently inhibited SPOP-mutated prostate cancer cell growth in preclinical investigations." (PMID 38201308, 2024). "SPOP is the most frequently mutated gene in primary prostate cancer, and its loss of function causes excessive accumulation of its substrates and deregulation." (PMID 38201308, 2024). "In a previous report, the accumulation of TOP2A induced by SPOP mutations was found to facilitate prostate cancer progression through the accumulation of DNA damage, and etoposide was found effective against SPOP-mutated prostate cancer." (PMID 38732035, 2024). "Recent studies have identified the tumor suppressor speckle-type POZ protein (SPOP) as frequently mutated in solid tumors, particularly prostate cancer." (PMID 38481812, 2024). "For initiation and early progression of primary prostate cancer, several driver mutations or alterations have been described e.g., inactivating SPOP mutations, activating FOXA1 mutations, TMPRRS-ERG fusion, loss of PTEN or AR alterations." (PMID 38704600, 2024). "In occurrence with CHD1 deletion, SPOP mutations define a distinct prostate cancer subtype, characterized by genomic instability, increased AR transcriptional activity, absence of ERG rearrangements, and increased DNA methylation." (PMID 36776288, 2023). "Loss-of-function mutations in SPOP elevated PD-L1 protein level, conferring to reduction of TILs in human prostate cancer tissues." (PMID 36733484, 2023). "SPOP is mutated in up to 15% of prostate cancers and these mutations have been shown to result in an inability of SPOP to associate with CDC20, preventing CDC20 protein turnover and consequently resistance to CDC20 inhibitors." (PMID 37509260, 2023). "For instance, Cullin3SPOP-targeted BRD4 ubiquitination promotes BRD4 protein degradation, while prostate cancer-associated SPOP mutants block this process." (PMID 37737256, 2023). "By associating MuAt features with driver events identified in PCAWG, MuAt highlighted prostate cancers driven by SPOP mutations, characterized by a 2.3-fold increase in somatic SV burden, exceeding the relative burden in tumours with BRCA1 and BRCA2 mutations." (PMID 37420249, 2023).
prostate carcinoma (continued). "In prostate cancer, mutations within the substrate binding site of SPOP were reported to mediate intrinsic resistance to BET inhibitors in vitro and in vivo." (PMID 37049806, 2023). "Prostate cancer-associated SPOP mutants (Y87C, Y87N, F102C, S119N, F125V, W131G, F133L, and F133V) fail to bind AR protein, thereby increasing the protein stability and activity of AR during tumorigenesis." (PMID 36776288, 2023). "All somatic mutations of SPOP identified in prostate cancers, including Y87C, F102C, W131G, and F133V, are situated within the MATH domain and demonstrate a dominant-negative influence on substrate binding and degradation." (PMID 37796126, 2023). "SPOP has a role in DNA damage response, and SPOP mutated prostate cancers have elevated levels of genomic instability." (PMID 37420249, 2023). "Mouse bearing the SPOP mutation F133V which is the most frequently found in prostate cancer patients, show little changes in their prostate." (PMID 36768610, 2023). "In prostate cancer, the loss-of-function mutation of SPOP (an E3 ubiquitin ligase of Brd4) has been shown to confer resistance to BET inhibitors by impairing ubiquitination-mediated Brd4 degradation." (PMID 37049806, 2023). "In prostate cancer, hotspot SPOP mutations are only observed in the MATH domain that is responsible for substrate recognition and recruitment." (PMID 36776288, 2023). "Prostate cancers with ERG driver mutations (n=85), mutually exclusive to SPOP (OR=0.102, 95% CI, 0.002–0.725, p=0.013;), were evenly distributed among the remaining prostate cancers in MuAt clustering." (PMID 37420249, 2023). "Strikingly, loss-of-function mutations in SPOP elevated PD-L1 protein level due to dysregulation of PD-L1 degradation, conferring to reduction of TILs in human prostate cancer tissues and mouse tumor samples." (PMID 36733484, 2023). "The BET protein degradation was substantially reduced in SPOP-mutated prostate cancer cells, leading to higher cellular BET protein expression." (PMID 37049806, 2023). "CHD1 deletion often co-occurs with missense mutations in SPOP (speckle-type BTB/POZ protein) and defines a new molecular subtype of prostate cancer, characterized by increased DNA methylation and homogeneous gene expression patterns." (PMID 36776288, 2023). "Speckle type BTB/POZ protein (SPOP) mutation is the most frequent point mutation in primary prostate cancer (~10%) and has been reported as an early clonal event as well as a distinct ETS-negative molecular subclass." (PMID 35050902, 2022). "Cancer genome analysis has identified recurrent missense mutations in the SPOP gene in 11~13% of primary prostate cancer (PC) and in 6~8% of metastatic and castration-resistant PC." (PMID 36115849, 2022). "For example, studies have demonstrated that BETi resistance is mediated by adaptive kinome reprogramming in ovarian cancer (OC), neuroblastoma, or SPOP-mutated prostate cancer." (PMID 35453346, 2022). "Specifically, DSBs induced by IR or the topoisomerase inhibitor camptothecin (CPT) become repaired via NHEJ, whereas homology directed repair (HDR) is impaired upon SPOP loss or mutation in prostate cancer cells." (PMID 35954292, 2022). "Although intensive researches have comprehensively described the roles of aberrant SPOP mutations or expressions on kidney cancer, prostate cancer and endometrial cancer, the specific roles of SPOP on hematologic tumors are still unclear." (PMID 35773729, 2022). "Speckle- type BTB/POZ protein (SPOP) mutations represent the most frequently identified type of genomic mutations in prostate cancer." (PMID 35954292, 2022). "SPOP mutations in prostate cancer result in impaired homology-directed repair of double strand breaks and are associated with genomic instability." (PMID 35975235, 2022).